HDAC1 (histone deacetylase 1)
Diseases named in the same sentence as HDAC1 in open-access papers (continued):
Sharing a sentence is not in itself a finding about the gene and the disease.
allergic disease (3 papers, 2022 to 2023). An immune response that occurs following re-exposure to an innocuous antigen, and that requires the presence of existing antibodies against that antigen. "On the other hand, inhibition of HDACs for example, by deletion of Hdac1 in mice exposed to the allergen caused more stable Th2 immune responses resulting in mucus hypersecretion by goblet cells, demonstrating an important role of HDAC1 in allergic diseases." (PMID 37251385, 2023). "On the other hand, HDAC1 is modulated by upstream transcription factors and signaling pathway in allergic diseases." (PMID 36311721, 2022). "Herein, we made a thorough review of recent studies and summarized the emerging functions of HDAC1 by regulating histone modifications and gene transcription in allergic disease." (PMID 36311721, 2022). "Besides, additional work is required to examine the expression and activity of HDAC1 in allergic diseases." (PMID 36311721, 2022). "The development of selective HDAC1 inhibitors may lead to new therapeutic agents for allergic diseases, particularly in situations where current therapies are suboptimal." (PMID 36311721, 2022).
amyotrophic lateral sclerosis (3 papers, 2015 to 2022). Amyotrophic lateral sclerosis (ALS) is a neurodegenerative disease characterized by progressive muscular paralysis reflecting degeneration of motor neurons in the primary motor cortex, corticospinal tracts, brainstem and spinal cord. "Familial mutations in FUS linked to amyotrophic lateral sclerosis (ALS) decrease an interaction with the histone deacetylase HDAC1 and produce a FUS protein defective in DNA repair and DDR." (PMID 26529031, 2015). "Intriguingly, several of the mutations in the FUS gene identified in familial cases of amyotrophic lateral sclerosis (F-ALS) are located in the regions implicated in the interaction with HDAC1." (PMID 25926848, 2015). "For instance, mutant R521C stabilizes FUS in amyotrophic lateral sclerosis (ALS) patients, facilitating its interaction with RBM45, and decreases the recruitment of HDAC1 to contribute to the pathogenesis of ALS16." (PMID 35654793, 2022).
Anxiety (3 papers, 2024 to 2025). Intense feelings of nervousness, tension, or panic often arise in response to interpersonal stresses. "The recovery of the anxiety-like phenotype in male BDNFV/V mice is associated with a greater long-term decrease in HDAC1 and Dnmt3a levels and a greater increase in pCREB and Bdnf4 levels in the hippocampus." (PMID 38785785, 2024). "Activation of HDAC1, HDAC3, and NADPH oxidase 4 (NOX4) influences prostaglandin production in the cortex via microglia, which is associated with heightened anxiety and altered glutathione metabolism." (PMID 39851502, 2025). "Our data are consistent with these findings, as we found a greater decrease in HDAC1 in the hippocampus of BDNFV/V mice than in BDNFV/M mice, which was associated with the disappearance of the anxiety-like phenotype only in BDNFV/V mice." (PMID 38785785, 2024). "While in male BDNFV/M mice the anxiety-like phenotype persisted for several days after FSS exposure, phenotype recovery in male BDNFV/V mice was accompanied by a decrease in HDAC1 and Dnmt3a and an increase in pCREB and Bdnf4." (PMID 38785785, 2024).
Arthritis (3 papers, 2017 to 2024). Inflammation of a joint. "In addition, inhibition of HDAC1 inhibits inflammation and bone loss in arthritis, and inhibitors targeting HDAC1 may be useful in the treatment of arthritis." (PMID 35794630, 2022). "In synovial fibroblasts from arthritis patients, HDAC1 siRNA enhanced TNFα-induced MMP-1 expression, whereas HDAC4 was identified as a negative regulator of MMP-1 expression." (PMID 28596772, 2017).
cholangiocarcinoma (3 papers, 2021 to 2023). A carcinoma that arises from the intrahepatic biliary tree (intrahepatic cholangiocarcinoma) or from the junction, or adjacent to the junction, of the right and left hepatic ducts (hilar cholangiocarcinoma). "Herein, we intend to explore the potential role of HDAC1 inhibitor (JSL-1) in the tumorigenesis and metastasis of cholangiocarcinoma (CC) and to highlight the molecular basis of its function." (PMID 35395834, 2022).
chronic renal failure (3 papers, 2020 to 2023). "LSD1, upon deacetylation by histone deacetylase 1 (HDAC1), reduced the methylations of H3K4me2 in the promoter region of Sesn2, thereby suppressed the gene expression of Sesn2 in chronic renal failure (CRF)." (PMID 33425907, 2020).
coronary heart disease (3 papers, 2023 to 2025). "HDAC1 is overexpressed in patients with coronary heart disease (CHD)." (PMID 40497340, 2025). "Another miRNA microarray analysis revealed that HDAC1 inhibition via shRNA led to miR-182 overexpression, which suppresses TGF-β/Smad pathway to alleviate coronary heart disease." (PMID 38983721, 2024). "Cardiac-specific KD of HDAC1 or HDAC9 was found cardioprotective in a sepsis model and a coronary heart disease model, or MI model, respectively." (PMID 38983721, 2024).
dilated cardiomyopathy (3 papers, 2017 to 2025). Cardiomyopathy which is characterized by dilation and contractile dysfunction of the left and right ventricles. "Simultaneous cardiac-specific deletion of HDAC1 and 2 results in the development of severe cardiac defects such as dilated cardiomyopathy and arrhythmias which lead to early neonatal lethality." (PMID 34723970, 2021). "Notably, cardiac-restricted deletion of both HDAC1 and HDAC2 caused dilated cardiomyopathy accompanied by upregulation of genes encoding skeletal muscle-specific contractile proteins." (PMID 28394251, 2017).
ductal carcinoma in situ (3 papers, 2013 to 2026). "Our results are in agreement with previous observations that have associated the reduction of HDAC1 transcript and protein levels with progression from normal mammary epithelium to ductal carcinoma in situ (DCIS) and to IDC." (PMID 23421821, 2013). "For instance, in 58 breast samples, acetylated histone H4, H4K12ac, acetylated tubulin, HDAC1, HDAC2, and HDAC6 were lower in ductal carcinoma in situ (DCIS) and invasive ductal carcinoma (IDC) than in normal mammary epithelium." (PMID 34595180, 2021).
embryonal carcinoma (3 papers, 2021 to 2025). A non-seminomatous malignant germ cell tumor characterized by the presence of large germ cells with abundant cytoplasm resembling epithelial cells, geographic necrosis, high mitotic activity, and pseudoglandular and pseudopapillary structures formation. "Several studies have shown potential interaction between SOX2 and MTA1/2/3, MBD2, GATAD2A/B, and HDAC1/2 in different cell lines, including embryonic stem cells, neural stem cells, and embryonal carcinoma cells." (PMID 35615634, 2022). "Hdac1 depletion stimulated cardiomyocyte formation, increased the levels of acetylated lysines and upregulated the expressions of GATA4 and NKX2.5 in ES cells and embryonal carcinoma cells." (PMID 33882103, 2021).
endometrial cancer (3 papers, 2020 to 2022). Primary or metastatic malignant neoplasm involving the endometrium (mucous membrane that lines the endometrial cavity). "High expression of HDAC1 has been linked to poor prognosis in endometrioid subtypes of ovarian and endometrial carcinomas." (PMID 33669182, 2021). "In endometrial cancer cells, PsA showed HDAC1 and HDAC6 inhibition, reduction of HDAC1 expression the elevation of histone H3 and H4 acetylation, induction of cell cycle arrest, and apoptosis." (PMID 33312959, 2020).
endothelial dysfunction (3 papers, 2020 to 2025). In vascular diseases, endothelial dysfunction is a systemic pathological state of the endothelium (the inner lining of blood vessels) and can be broadly defined as an imbalance between vasodilating and vasoconstricting substances produced by (or acting on) the endothelium. "We provide evidence that under diabetic conditions, overexpression of miR-570-3p alleviates endothelial dysfunction by reducing HDAC1 expression and endothelial inflammatory injury, thereby reducing endothelial dysfunction." (PMID 36120375, 2022).
epilepsy (3 papers, 2022 to 2024). A brain disorder characterized by episodes of abnormally increased neuronal discharge resulting in transient episodes of sensory or motor neurological dysfunction, or psychic dysfunction. "The inhibitory effects of HDAC1 and HDAC10 expressions were also observed in the zebrafish epilepsy model triggered by a GABAARγ 2 subunit (GABRG2) mutation after treatment with SAHA." (PMID 39563472, 2024). "In the WAG/Rij epilepsy rat model, a genetic model of absence epilepsy, epileptogenesis, and mild-depression comorbidity, the acetylated levels of H3 and H4 histones were increased significantly and the decreased expressions of HDAC1 and HDAC3 were observed following NaB treatment." (PMID 39563472, 2024). "Lacosamide (LCM), a novel drug with the reduction of HDAC1 protein expression in preclinical studies was licensed in 2008 by FDA/EMA as an adjunctive treatment for curing partial-onset seizures in adolescent patients attacked by epilepsy." (PMID 39563472, 2024).
fibrosarcoma (3 papers, 2013 to 2017). A malignant mesenchymal fibroblastic neoplasm affecting the soft tissue and bone. "HDAC1 was shown to be recruited to the MMP-9 promoter site, reducing histone H3 acetylation and NF-κB recruitment, leading to repression of MMP-9 expression in fibrosarcoma cells." (PMID 28596772, 2017). "In corroboration with previous studies in primary cells, deletion of Hdac1 alone or knockdown of Hdac2 alone in fibrosarcoma cells did not result in any increase in H4K5ac." (PMID 23947532, 2013).
HCMV infection (3 papers, 2010 to 2018). "PML was required for accumulation of activated STAT1 and STAT2, interacted with them and HDAC1 and HDAC2, and was associated with ISG promoters after HCMV infection." (PMID 25812002, 2015). "We have used a focused proteomics approach to identify proteins that are interacting with and regulating the histone deacetylase 1 (HDAC1) protein during acute cytomegalovirus infection." (PMID 20585571, 2010). "Furthermore, after UV-HCMV infection, PML formed a protein complex with STAT1, STAT2, HDAC1, and HDAC2 and associated with ISG promoters." (PMID 25812002, 2015). "Furthermore, we found that during HCMV infection IE1 reduced the association of PML, STAT2, and HDAC1 with ISG promoters." (PMID 25812002, 2015). "Since PML directly interacts with HDAC1 and HDAC2, which may affect ISG transcription, we also assessed whether PML associates with these HDACs after UV-HCMV infection." (PMID 25812002, 2015). "Notably, PML has been reported to mediate the recruitment of activated STAT1 and 2, along with HDAC1 and 2, onto ISG promoters (ISG54, CXCL10) during human cytomegalovirus (HCMV) infection." (PMID 29309427, 2018).
Hepatitis (3 papers, 2022 to 2025). Inflammation of the liver. "Meanwhile, we observed that in hepatitis-related HCC, patients with higher expression of BCL2L1, EGFR, ESR1, HNF4A, MAPK8, and PTEN, and lower expression of HDAC1 had a better clinical prognosis." (PMID 36133813, 2022).
HIV-1 infection (3 papers, 2009 to 2019). The type species of lentivirus and the etiologic agent of acquired immunodeficiency syndrome (AIDS). "Since both IN and INI1 bind to SAP18, it is possible that association of INI1 with SAP18-Sin3a-HDAC1 complex is increased upon HIV-1 infection." (PMID 19503603, 2009).
idiopathic pulmonary arterial hypertension (3 papers, 2020 to 2023). A sporadic form of pulmonary arterial hypertension (PAH) characterized by elevated pulmonary arterial resistance leading to right heart failure. "One study reported that the expression levels of HDAC1, HDAC2, and HDAC8 were upregulated in patients with idiopathic pulmonary arterial hypertension." (PMID 35126818, 2022). "Comprehensive analysis of expression and regulation of class I HDACs (HDAC1, HDAC2, HDAC3 and HDAC8) was performed in cardiopulmonary tissues and adventitial fibroblasts isolated from pulmonary arteries (PAAF) of idiopathic pulmonary arterial hypertension (IPAH) patients and healthy donors." (PMID 32733053, 2020).
insulinoma (3 papers, 2008 to 2013). "It has been reported that Sox6 inhibits cyclin D1 expression by interacting with β-catenin and HDAC1 in insulinoma INS-1E and NIH-3T3 cells and that down-regulation of cyclin D1 is important for cell cycle exit." (PMID 24040263, 2013). "Glucose-regulated interactions between Hdac1/2, Pdx1 and/or Sox6 have been suggested to control insulin gene expression in mouse insulinoma cell lines." (PMID 18687323, 2008).
kidney cancer (3 papers, 2021 to 2025). Primary or metastatic malignant neoplasm involving the kidney. "Studies with SAP30 gene have shown its relationship with histone deacetylase process in eukaryotes that induces Sin3, the histone deacetylases HDAC1 and HDAC2, and acting as a transcription factor for NETO2 gene in kidney cancer." (PMID 34646299, 2021). "HDAC1 and HDAC2 are necessary for the growth and survival of kidney cancer cells." (PMID 41407823, 2025).
mesenchymal tumors (3 papers, 2021 to 2023). "Similar findings regarding HDAC-1 have been reported in skin melanoma and in mesenchymal tumors, suggesting that HDAC-2 is the class I isoform more likely associated with the pathogenesis of UMs." (PMID 34638249, 2021). "Additionally, HDAC-1 was the least frequently expressed isoform in comparison to the rest of mesenchymal tumors." (PMID 34441281, 2021). "Finally, Pacheco and O Nielsen tried to elucidate the role of HDAC-1 and HDAC-2 in a large series of mesenchymal tumors, comprised of 1332 cases, representing 44 categories of both malignant and borderline tumors." (PMID 34441281, 2021).
Non-Alcoholic Fatty Liver Disease (3 papers, 2021 to 2025). "Additionally, another study indicated that Danshensu protects against nonalcoholic fatty liver disease by significantly enhanced fatty acid β-oxidation and decreased lipid droplet accumulation in the histone deacetylase 1/TATA-box binding protein associated factor 9-dependent pathway." (PMID 40225863, 2025).
ovarian tumors (3 papers, 2007 to 2014). "R306465 was identified as potent novel hydroxamate-based inhibitor of histone deacetylase 1 (HDAC1) inhibiting immunoprecipitated HDAC1 complexes in vitro with an IC50 value of 3.3 nM and A2780 ovarian tumour cell proliferation with an IC50 of 39 nM." (PMID 18000499, 2007).
Parkinson disease (3 papers, 2022 to 2025). A progressive degenerative disorder of the central nervous system characterized by loss of dopamine producing neurons in the substantia nigra and the presence of Lewy bodies in the substantia nigra and locus coeruleus. "In Parkinson’s disease, reduced Nrf2 signaling accelerates dopaminergic neuron loss, and heightened HDAC1 activity contributes to mitochondrial dysfunction and α-synuclein aggregation." (PMID 40650264, 2025). "A recent study on Parkinson’s disease (PD) indicates that the abnormal transportation of HDAC1 from the nucleus to the cytoplasm could be one of the causes of the axonopathy and abnormal motor behavior in PD patients." (PMID 36358670, 2022).
pituitary adenomas (3 papers, 2019 to 2024). "Of note, it has been reported that the high levels of HDAC1, 2, and 11 were detected in pituitary adenoma cells." (PMID 38637883, 2024). "We also examined HDAC1, HDAC2, and HDAC3 expression by qRT-PCR in six GH-secreting, six ACTH-secreting, and six PRL-secreting human pituitary adenomas." (PMID 35646715, 2022).
retinoblastoma (3 papers, 2018 to 2025). A malignant tumor that originates in the nuclear layer of the retina. "Another hub protein identified in all four regenerative PPI networks was Hdac1, which interacts with retinoblastoma tumor-suppressor protein, forming a complex that is key in the control of cell proliferation and differentiation." (PMID 29560825, 2018). "Retinoblastoma (RB) promotes histone deacetylation and gene silencing via recruiting HDAC5 or HDAC1 under different circumstances." (PMID 40659605, 2025).
stomach adenocarcinoma (3 papers, 2022 to 2023). "The other six hub genes have no gene mutation records in STAD-related research, but HDAC1 and ESR1 genes have been confirmed to be related to the occurrence and prognosis of gastric adenocarcinoma, associated with the patients’ DFS and OS." (PMID 35686089, 2022). "In addition, we found that the expression of ESR1, HDAC1, and CLTC genes in patients with stomach adenocarcinoma may be related to poor prognosis and lower overall survival." (PMID 35686089, 2022).
urothelial bladder carcinoma (3 papers, 2019 to 2024). "Both HDAC1 and HDAC2 were significantly associated with higher tumor grades of urothelial bladder carcinoma." (PMID 39063083, 2024).
urothelial carcinoma (3 papers, 2014 to 2020). A malignant neoplasm derived from the transitional epithelium of the urinary tract (urinary bladder, ureter, urethra, or renal pelvis). "In urothelial carcinoma, in particular, the importance of class I HDACs, especially of HDAC1 and HDAC2, has been underlined by recent dedicated studies, in keeping with general thought." (PMID 31052182, 2019). "High HDAC expression levels were found in 40 to 60% of all investigated urothelial carcinomas (HDAC-1: 40%, HDAC-2: 42%, HDAC-3: 59%)." (PMID 24624923, 2014).
-thalassaemia (2 papers, 2009 to 2018). "DAXX has been found to be associated with multiple proteins involved in transcriptional repression, such as HDAC1, DNA methyltransferase 1 (DMNT1), and α-thalassaemia/mental retardation syndrome X-linked (ATRX)." (PMID 30336783, 2018).
acute lymphoblastic leukemia (2 papers, 2025). Leukemia with an acute onset, characterized by the presence of lymphoblasts in the bone marrow and the peripheral blood. "HDAC1/2 inhibitors trigger apoptosis in acute lymphoblastic leukemia, while HDAC3 inhibitors are more effective in T‐cell lymphoma cell lines, suggesting that selectively targeting HDAC1/2/3 might be beneficial in certain disorders." (PMID 40801055, 2025).
adenoma (2 papers, 2013 to 2025). A neoplasm arising from the epithelium. "In terms of HDAC1 expression, differences were noted among groups G1 and G2 (p=0.002), G1 and G4 (p < 0.001), and G3 and G4 (p=0.010), with higher expression in normal mammary tissue compared to simple adenomas and metastatic carcinomas." (PMID 40590021, 2025). "We performed a PCR array for HDAC1, HDAC2, HDAC3, HDAC5 and HDAC7 on human rectal biopsies from patients with or without an adenoma in the colon (n = 86 subjects total)." (PMID 23724067, 2013).
adenomyosis (2 papers, 2021 to 2023). The growth of endometrial tissue inside the muscular wall of the uterine corpus. "However, in group 3 (patients with adenomyosis), the relative content of HDAC1 was 23% lower than it was in the control (p < 0.05)." (PMID 34440202, 2021). "Indeed, the expression of HDAC1 and HDAC3 was increased in the eutopic and ectopic endometrium of adenomyosis patients compared to controls." (PMID 37763670, 2023). "There was a decrease in the HDAC1 content in the group with adenomyosis, but there were no changes in the tubulin content in this group." (PMID 34440202, 2021).
adrenal cortical carcinoma (2 papers, 2019 to 2023). "Epigenetically plastic SW13 adrenocortical carcinoma cells were treated with FK228, an HDAC inhibitor with high affinity for HDAC1 and, to a lesser extent, HDAC2." (PMID 30651077, 2019). "Interestingly, incubation of human adrenal cortical carcinoma cells with a class I HDAC inhibitor promotes EMT in these cells, supporting the idea that HDAC1 may act as a suppressor of EMT." (PMID 37414747, 2023).